DENND6B (DENN domain containing 6B)
Description:
Guanine nucleotide exchange factor (GEF) for RAB14. Also has some, lesser GEF activity towards RAB35.
Synonyms: FAM116B; MGC33692; AFI1B
Tractability: Antibody: the Human Protein Atlas places it where antibodies can reach. PROTAC: ubiquitination databases record sites on it; its protein half-life has been measured.
Gene: Protein-coding gene on chromosome 22 (50,309,030 to 50,327,521, reverse strand). Ensembl gene ENSG00000205593.
Subcellular location: Recycling endosome; Cytoplasm
Subcellular location (Human Protein Atlas): Plasma membrane
Pathways (Reactome):
Vesicle-mediated transport: RAB GEFs exchange GTP for GDP on RABs
Gene Ontology:
Molecular function: guanyl-nucleotide exchange factor activity
Cellular component: cytosol; recycling endosome; cytoplasm
Genetic constraint (gnomAD): Loss-of-function variants: 73 observed, 73.2 expected, observed/expected ratio (o/e) 1, 90% interval 0.82 to 1.21. The synonymous counts are far from expectation, so gnomAD's model fits this gene poorly and the ratio says little. Missense variants: 715 observed, 672.59 expected, observed/expected ratio (o/e) 1.06, 90% interval 1 to 1.13. Synonymous variants: 357 observed, 278.24 expected, observed/expected ratio (o/e) 1.28, 90% interval 1.18 to 1.4.
Homologues: Orthologues: chimpanzee DENND6B (99% identical), guinea pig DENND6B (91% identical), mouse Dennd6b (91% identical), rat Dennd6b (91% identical), dog DENND6B (91% identical), pig DENND6B (88% identical), rabbit DENND6B (85% identical), macaque DENND6B (71% identical), zebrafish dennd6b (69% identical), tropical clawed frog dennd6b (62% identical), Drosophila melanogaster CG3309 (46% identical), Caenorhabditis elegans F53H1.3 (41% identical). Paralogues in human: DENND6A (58% identical).
Diseases named in the same sentence as DENND6B in open-access papers:
DENND6B is named in the same sentence as 2 diseases in open-access papers, as found by Europe PMC text mining. Sharing a sentence is not in itself a finding about the gene and the disease. The quoted sentences say what the papers report.
colorectal cancer (1 paper, 2021). A primary or metastatic malignant neoplasm that affects the colon or rectum. "Moreover, the role of DENND6B, NCOA7and TMCO6 in cancer is largely unknown, our results indicated their important role in colorectal cancer; further studies are expected to reveal their biological function." (PMID 34035992, 2021).
DENND6B also shares sentences with these, for which no sentence is quoted: cancer (1 paper).